ZNF750 (zinc finger protein 750)
Description:
Transcription factor involved in epidermis differentiation. Required for terminal epidermal differentiation: acts downstream of p63/TP63 and activates expression of late epidermal differentiation genes. Specifically binds to the promoter of KLF4 and promotes its expression.
Synonyms: FLJ13841; Zfp750; SLDPE
Tractability: No criterion of Open Targets' tractability assessment is met for any kind of drug.
Gene: Protein-coding gene on chromosome 17 (82,829,434 to 82,840,022, reverse strand). Ensembl gene ENSG00000141579.
Subcellular location: Nucleus
Pathways (Reactome):
Gene expression (Transcription): Generic Transcription Pathway
Gene Ontology:
Molecular function: DNA-binding transcription activator activity, RNA polymerase II-specific; DNA-binding transcription repressor activity, RNA polymerase II-specific; promoter-specific chromatin binding; protein binding; RNA polymerase II cis-regulatory region sequence-specific DNA binding
Biological process: epidermis development; negative regulation of epithelial to mesenchymal transition; negative regulation of transcription by RNA polymerase II; positive regulation of transcription by RNA polymerase II; regulation of transcription by RNA polymerase II
Cellular component: nucleus
Genetic constraint (gnomAD): Loss-of-function variants: 12 observed, 35.11 expected, observed/expected ratio (o/e) 0.34, 90% interval 0.22 to 0.55. The upper end of that interval is the gene's LOEUF score, 0.55, which puts it in group 2 of 6, group 1 being the genes least tolerant of losing a copy. Missense variants: 914 observed, 986.42 expected, observed/expected ratio (o/e) 0.93, 90% interval 0.88 to 0.98. Synonymous variants: 400 observed, 428.44 expected, observed/expected ratio (o/e) 0.93, 90% interval 0.86 to 1.01.
Homologues: Orthologues: chimpanzee ZNF750 (98% identical), macaque ZNF750 (94% identical), dog ZNF750 (72% identical), rat Znf750 (71% identical), mouse Zfp750 (70% identical), guinea pig ZNF750 (68% identical), rabbit ZNF750 (67% identical), pig ZNF750 (62% identical), tropical clawed frog znf750 (42% identical), zebrafish znf750 (22% identical). Paralogues in human: PRR35 (15% identical), NHLRC4 (3% identical).
Diseases named in the same sentence as ZNF750 in open-access papers:
ZNF750 is named in the same sentence as 43 diseases in open-access papers, as found by Europe PMC text mining. Sharing a sentence is not in itself a finding about the gene and the disease. The quoted sentences say what the papers report.
squamous cell carcinoma (11 papers, 2017 to 2023). A carcinoma arising from squamous epithelial cells. "These are very promising findings: whereas ZNF750 is a lineage-specific tumor suppressor in squamous cell carcinoma, COL1A1 is associated with many tumor entities including oral and pancreatic cancer with prognostic relevance." (PMID 37455825, 2023). "Indeed, ZNF750 is underexpressed in squamous cell carcinoma, and low levels of ZNF750 are associated with poor survival." (PMID 37047491, 2023). "In addition, ZNF750 is associated with better survival and functions as a tumor suppressor in melanoma, nasopharyngeal carcinoma, oral squamous cell carcinoma, and squamous cell carcinoma." (PMID 37365152, 2023). "Moreover, in human squamous cell carcinomas (SCCs) (head and neck, esophagus, cervix, and lung), missense and truncating mutations as well as genomic deletions of the ZNF750 locus have been described." (PMID 37047491, 2023). "Earlier researches reported that ZNF750 is typically mutated or deleted in squamous cell carcinoma." (PMID 34176441, 2021). "ZNF750 is largely mutated or deleted in squamous cell carcinomas." (PMID 29416636, 2018). "In addition, through cBioPortal based on the Cancer Genome Atlas (TCGA) or other cancer genome database, we found that the inactivating mutation rates of ZNF750 in different squamous cell carcinomas (SCC) were much higher than those in the corresponding adenocarcinomas." (PMID 32042337, 2020). "As for ZNF750 is a newly found lineage-specific tumor suppressor in squamous cell carcinoma, there is still a great deal of work to be done to identify the effect of ZNF750 on OSCC." (PMID 29416636, 2018). "ZNF750 is a tumor suppressor in squamous cell carcinoma, which can suppress cell migration." (PMID 36726580, 2023). "ZNF750 (zinc finger protein 750) which is described as a tumor suppressor gene in squamous cell carcinoma, is as well subject to high positive selection (dN/dS ratio > 50) in regions of LOH in lung squamous cell carcinoma (LUSC) and head and neck squamous cell carcinoma (HNSC)." (PMID 33450833, 2021). "Finally, we explored the correlation of ZNF750 with FOXC2 expression level across various human squamous cell carcinomas." (PMID 32341351, 2020). "Importantly, we performed RNA-sequencing of paired fresh tumor tissues and matched adjacent non-cancerous specimens from 97 ESCC subjects; together with available TCGA data, we validated the associations among ZNF750 and the identified downstream targets in ESCC and other squamous carcinomas." (PMID 32341351, 2020). "Additionally, we also conducted the correlation analysis of ZNF750 with FOXC2 transcriptional level in ESCC and other squamous cell carcinomas based on the TCGA database." (PMID 32341351, 2020).
esophageal squamous cell carcinoma (8 papers, 2020 to 2025). Esophageal squamous cell carcinoma (ESCC) is a type of esophageal carcinoma (EC) that can affect any part of the esophagus, but is usually located in the upper or middle third. "In metastasis, DANCR was recently found to be a direct target of zinc finger protein 750 (ZNF750), a tumor suppressor gene mutated/deleted in patients with esophageal squamous cell carcinoma (ESCC)." (PMID 36831169, 2023). "ZNF750 is one novel significantly mutated gene identified in esophageal squamous cell carcinoma (ESCC) using next-generation sequencing." (PMID 32341351, 2020). "More recent work has found that knockdown of the ZNF750 gene significantly promoted cell proliferation, colony formation, migration and invasion in esophageal squamous cell carcinoma cells." (PMID 35003347, 2021). "ZNF750 is reported to exhibit tumor-suppressive effects in esophageal squamous cell carcinoma and oral squamous cell carcinoma." (PMID 34288812, 2021). "ZNF750 also suppresses the progression of other malignancies such as esophageal squamous cell carcinoma." (PMID 34288812, 2021). "In esophageal squamous cell carcinoma (ESCC), ZNF750 suppresses ITGB1 transcription while SIPA1 inhibits the ITGB1 expression." (PMID 38279122, 2024). "In a murine study, miR-4707-3p was found to interact with DANCR to regulate the expression of FOXC2 oncogene, in a zinc finger protein 750 (ZNF750) dependent manner, which affected esophageal squamous cell carcinoma angiogenesis." (PMID 41039543, 2025).
oral squamous cell carcinoma (7 papers, 2018 to 2023). "Previous RNA sequence analysis (GSE134835) revealed E2F2 was significantly reduced by Zinc-finger protein 750 (ZNF750) in oral squamous cell carcinoma (OSCC)." (PMID 35003347, 2021). "Zinc-finger protein 750 (ZNF750) is the potential anti-cancer gene in oral squamous cell carcinoma (OSCC)." (PMID 29416636, 2018). "The ability of resveratrol to suppress the progression of oral squamous cell carcinoma may involve activation of the ZNF750/RAC1 signaling pathway and modification of the tumor vascular microenvironment." (PMID 34176441, 2021). "To confirm the molecular mechanism of resveratrol in suppressing the malignant progression of oral squamous cell carcinoma cells, we further determined the expression levels of ZNF750 and RAC1 in CAL-27 cells after treatment with different concentrations of resveratrol." (PMID 34176441, 2021). "In summary, resveratrol could regulate the tumor vascular microenvironment to suppress the oral squamous cell carcinoma malignant process through the activation of ZNF750/RAC1 signaling pathway." (PMID 34176441, 2021). "This study examined whether activation of zinc finger protein 750/Ras-related C3 botulinum toxin substrate 1 (ZNF750/RAC1) signaling pathway may be involved in the ability of resveratrol to inhibit malignant progression of CAL-27 oral squamous cell carcinoma cells." (PMID 34176441, 2021).
psoriasis (7 papers, 2011 to 2024). An autoimmune condition characterized by red, well-delineated plaques with silvery scales that are usually on the extensor surfaces and scalp. "We have previously demonstrated that a dominant mutation in ZNF750 leads to a clinical phenotype reminiscent of psoriasis and seborrheic dermatitis." (PMID 22936986, 2012). "ZNF750 has previously been reported to be associated with autosomal dominant forms of psoriasis or psoriasiform dermatitis in two separate, multigenerational families." (PMID 22185198, 2011). "ZNF750 encodes a putative zinc finger transcription factor that is highly expressed in keratinocytes and represents a candidate psoriasis gene." (PMID 22185198, 2011). "We sequenced a total of 1,113 individuals (716 Caucasian psoriasis cases and 397 ethnically matched healthy controls) in the promoter and exonic regions of ZNF750 and identified 47 polymorphisms, of which 35 were novel." (PMID 22185198, 2011). "As ZNF750 resides in the PSORS2 region and has been previously reported to cause familial psoriasis forms of psoriasis, we were motivated to evaluate ZNF750 in a large cohort of cases and controls." (PMID 22185198, 2011). "Mutations in the ZNF750 promoter and coding regions have been previously associated with Mendelian forms of psoriasis and psoriasiform dermatitis." (PMID 22185198, 2011). "Functional assays demonstrated that 4 of these variants decreased ZNF750 promoter activity in accordance with previous reports in psoriasis and psoriasiform dermatitis." (PMID 22185198, 2011). "One candidate susceptibility gene for psoriasis is ZNF750, a gene located at chromosome 17q25 within the PSORS2 locus." (PMID 22185198, 2011). "In the same study, the promoter variant c.-625A>C was linked to a multigenerational Taiwanese psoriasis family and was reported to reduce ZNF750 promoter activity by 42%." (PMID 22185198, 2011). "We also observed a nominal association between rare variants in the 5' regulatory region of ZNF750 and psoriasis." (PMID 22185198, 2011). "Two haplotypes of ZNF750 and rare 5' regulatory variants of ZNF750 were found to be associated with psoriasis." (PMID 22185198, 2011). "To analyze the significance of the identified ZNF750 variations/mutations in psoriasis patients, we first tested each variant alone using a Fisher's exact test." (PMID 22185198, 2011). "There is some evidence that ZNF750 might play a role also in bone fide psoriasis since ZNF750 regulatory variants have been identified in classic forms of psoriasis." (PMID 22936986, 2012). "Association testing identified two ZNF750 haplotypes associated with psoriasis (p < 0.05)." (PMID 22185198, 2011). "Variants in the promoter and 5' UTR of ZNF750 which decrease ZNF750 expression might therefore be associated with a seborrheic form of psoriasis." (PMID 22185198, 2011). "The first is that certain 5' regulatory variants in ZNF750 could serve as a genetic modifier of the psoriasis phenotype or act as an incremental risk modifier similar to the common susceptibility alleles previously identified." (PMID 22185198, 2011). "To determine whether ZNF750 is associated with psoriasis, we sequenced ZNF750 in 716 Caucasian psoriasis cases and 397 Caucasian controls." (PMID 22185198, 2011). "Therefore, in order to more rigorously evaluate the possible association of rare variants in ZNF750 with psoriasis, we used the weighted-sum approach of Madsen and Browning to evaluate functional groups of rare variants for disease association." (PMID 22185198, 2011). "We examined whether ZNF750 variants were associated with psoriasis in a large case-control population." (PMID 22185198, 2011). "Since Mendelian-pattern psoriasis in these two large families is associated with ZNF750, we sought to examine whether variants in ZNF750 might influence the development of psoriasis in a larger population." (PMID 22185198, 2011).
psoriasis (continued). "To assess whether psoriasis patients with 5' regulatory variants have a similar clinical phenotype, we clinically characterized the psoriasis patients with the ZNF750 5' variants." (PMID 22185198, 2011). "Interestingly alteration of ZNF750 transcriptional regulation network during keratinocyte differentiation, caused by ZNF750 mutations, is involved in the development of diseases, such as psoriasis." (PMID 29152378, 2017). "Next, we evaluated whether common variant haplotypes of ZNF750 were associated with psoriasis." (PMID 22185198, 2011). "It has been reported that Zinc-finger protein family members, such as ZNF750, were related to skin diseases and the pathogenesis of seborrhea-like dermatitis and psoriasis in humans and the promotion of ZNF750 is potentially related to skin diseases." (PMID 39695421, 2024). "Mutations in these genes lead to human genetic skin diseases such as epidermolytic hyperkeratosis (KRT1), ichthyosis vulgaris (FLG), seborrheic dermatitis (ZNF750), psoriasis (LCE3D), and harlequin ichthyosis (ABCA12)." (PMID 34543262, 2021). "Herein, we genotyped ten common variants of ZNF750, Rptor and TRAF31P2 genes in our case–control cohort (n = 1034) from Polish population and evaluated main clinical phenotypes of psoriasis." (PMID 24005976, 2014). "However, our finding that two ZNF750 haplotypes were significantly associated with psoriasis suggests the possibility that other SNPs on 17q in LD with these haplotypes could possibly be associated with psoriasis." (PMID 22185198, 2011). "ZNF750 is highly expressed in keratinocytes, which are the major skin cell type affected both in seborrheic dermatitis and in psoriasis." (PMID 22185198, 2011). "In summary, we have performed the first re-sequencing study of the candidate psoriasis gene ZNF750 in a large case-control population." (PMID 22185198, 2011). "We sequenced the promoter and exon regions of ZNF750 in 716 Caucasian psoriasis cases and 397 Caucasian controls." (PMID 22185198, 2011). "Due to paucity and partial divergence of the ZNF750 and RPTOR literature data, it is justified to perform population-based association study to evaluate possible link between selected mutations/polymorphisms of these genes and psoriasis." (PMID 24005976, 2014). "Authors observed a nominal association between rare variants in the 5′ regulatory region of ZNF750 and psoriasis; however, these variants did not segregate with the psoriasis phenotype within families." (PMID 24005976, 2014). "In this study, we investigated whether variants within the ZNF750 promoter, 5' UTR, coding regions, and 3' UTR were associated with psoriasis in a Caucasian population." (PMID 22185198, 2011). "Alternatively, it is possible that there is no true association of 5' regulatory variants in ZNF750 with psoriasis and that the nominal association observed is the result of type I error." (PMID 22185198, 2011). "Although no individual variants were found to associate with psoriasis, two ZNF750 haplotypes showed a significant association." (PMID 22185198, 2011). "Seven rare variants in the 5' regulatory region of ZNF750 were seen in the psoriasis cases and none of these were present in the controls." (PMID 22185198, 2011). "We ascertain no connection of RPTOR and ZNF750 variants with psoriasis or its subphenotypes." (PMID 24005976, 2014). "Study results do not add evidence of RPTOR and ZNF750 as psoriasis susceptibility genes." (PMID 24005976, 2014). "We ascertain no connection of RPTOR and ZNF750 variants with psoriasis." (PMID 24005976, 2014). "In this case, the functional effects of these variants on ZNF750 promoter activity demonstrated here may not translate into biological relevance for psoriasis." (PMID 22185198, 2011). "Consistent with these trends, psoriasis-specific and non-specific DEGPs were oppositely regulated by RNA interference treatments targeting pro- and anti-differentiation genes, respectively (e.g., SNAI2, ANCR, STAU, ZNF750)." (PMID 26251673, 2015).
nasopharyngeal carcinoma (6 papers, 2018 to 2023). A carcinoma arising from the nasopharyngeal epithelium. "Only a single study has reported that m6A is associated with nasopharyngeal carcinoma in which m6A-mediated ZNF750 repression facilitates NPC progression." (PMID 32547941, 2020). "ZNF750 is mainly expressed in squamous epithelial cells, with a nuclear localization signal and a conserved C2H2 zinc finger domain, and has been reported to correlate with the prognosis of ESCC, colonic cancer, and nasopharyngeal carcinoma patients." (PMID 36452490, 2022).